SOX2 (SRY-box transcription factor 2)
Diseases named in the same sentence as SOX2 in open-access papers (continued):
Sharing a sentence is not in itself a finding about the gene and the disease.
ovarian carcinoma (continued). "Lentiviral re-expression of ectopic SOX2 reversed chemotherapy sensitivity, demonstrating that SOX2 may be a molecular driver for chemoresistance in ovarian cancer." (PMID 36551731, 2022). "Furthermore, Ibrutinib decreased BTK phosphorylation and Sox2/Bcl-xL expression in ovarian cancer, diminishing their self-renewal capacities and proportion of cancer stem cells." (PMID 36145624, 2022). "However, a clear connection has been established between increased expression of SOX2 and chemoresistance, not only in ovarian cancer but also in breast and prostate cancer." (PMID 36551731, 2022). "Moreover, in many types of cancer, the overexpression of SOX2 correlates with tumor invasions, such as melanoma, ovarian cancer, hepatocellular carcinoma, and laryngeal cancer." (PMID 36293387, 2022). "In contrast, trametinib treatment of PEO4 cells for 10 h significantly promoted the expression of cell stemness regulators SOX2, NANOG, POU5F1 (OCT4), and two ALDH1A homologs associated with elevated chemoresistance and the stem-like phenotype of ovarian cancer cells." (PMID 33803586, 2021). "To address this deficiency, we investigated SOX2, OCT4, and NANOG expression in a panel of ovarian cancer cell lines to identify correlations with growth properties, spheroid-forming potential, traditional TIC marker expression, tumorigenesis, and chemoresistance." (PMID 33445692, 2021). "In contrast, silencing of SOX2 in A2780-derived ovarian CSCs significantly reduced stem cell marker expression and decreased resistance to chemotherapy drugs such as doxorubicin or paclitaxel, as in ovarian cancer patient-derived sphere cells." (PMID 34064635, 2021). "We previously found that PGCCs could form spheroids in stem cell medium and acquired embryonic stemness marked by expression of OCT4, NANOG, and SOX2, which are involved in ovarian cancer relapse." (PMID 34588424, 2021). "Including SOX2 in evaluation of ovarian cancer TICs may improve reliability of TIC markers and our understanding of mechanisms of relapse." (PMID 33445692, 2021). "Moreover, KDM3A and Sox2 expression are both increased in ovarian cancer than in the normal tissues, and their expression is positively correlated with each other." (PMID 32354028, 2020). "Therefore, this PRL-3-HDAC4-MEF2A/histones-SOX2 signaling axis would be a potential therapeutic target in inhibiting ovarian cancer metastasis and relapse." (PMID 31887658, 2020). "In addition, pluripotent stem cell markers of normal stem cells, notably OCT4, NANOG and SOX2, have also been found to play an important role in ovarian cancer development and metastasis and can be used to verify cell stemness." (PMID 32169072, 2020). "Interestingly, a study in a human ovarian cancer cell line reported that Sox2 promotes cancer cell migration, invasion and colony formation through the up-regulation of FN36." (PMID 32029747, 2020). "SOX2+ cells in ovarian cancers could retain in vivo tumor-initiating capability and were responsible for therapy resistance and tumor aggressiveness." (PMID 30517668, 2020). "Therefore, KDM3A epigenetically activates Sox2 expression and promotes ovarian cancer stemness by removing repressive histone marks." (PMID 32354028, 2020). "Furthermore, KDM3A contributes to ovarian cancer stemness in cisplatin-resistant cells through the regulation of pluripotent proteins such as Sox2, Nanog, Oct4, and Lin28." (PMID 32354028, 2020). "Furthermore, the ovarian cancer cell lines within the NCI-60 panel showed a clear correlation between SOX2 and ST6GAL1 CNGs." (PMID 31610800, 2019). "Furthermore, protein levels of Sox2 and ST6Gal-I were found to strongly correlate in established ovarian cancer cell lines." (PMID 31610800, 2019). "We next evaluated levels of Sox2 and ST6Gal-I protein in multiple ovarian cancer cell lines." (PMID 31610800, 2019). "Thus, LSD1 is a critical factor in ovarian carcinoma cell growth and differentiation via a Sox2-mediated histone demethylation mechanism." (PMID 30064416, 2018).
ovarian carcinoma (continued). "For example, in the case of an ovarian cancer cell line, the side population exhibited elevated levels of SOX2 mRNA and a higher percentage of TIC when assayed using a limiting cell dilution tumor assay, the gold standard for assessing the frequency of TIC within a tumor." (PMID 28388544, 2017). "Moreover, KDM3A is abundantly expressed and positively correlated with Sox2 expression in human ovarian cancer tissues." (PMID 27694900, 2017). "Furthermore, in a SOX2-expressing ovarian cancer cell line, SOX2 knockdown using short hairpin RNAs (shRNA) provided susceptibility to these drugs, which was reversed upon re-expression of SOX2 ectopically." (PMID 28388544, 2017). "In human ovarian carcinoma, SOX2 expression showed correlation with stem cell state." (PMID 27489349, 2016). "Importantly, SOX2 overexpression was shown to be a poor prognostic marker in ovarian cancer and also shown to be involved in taxane resistance." (PMID 27049920, 2016). "Though broader spectrum of CSCs may need to be tested to evaluate how common FOXP1 to core CSC transcription network, FOXP1 up-regulates expression of CSC-related core transcription factors, including ABCG2, OCT4, NANOG, and SOX2, in ovarian cancer cells." (PMID 26654944, 2016). "Spheres from primary ovarian cancer tissues showed high expression of SOX2." (PMID 27489349, 2016). "In addition, NOTCH signaling was necessary for hypoxia-induced augmentation of CSC characteristics and SOX2 was necessary for hypoxia- or NICD-induced augmentation of CSC characteristics in ovarian cancer cells." (PMID 27489349, 2016). "A study using human ovarian cancer cell lines also suggested that the expression of Sox2 might account for cellular resistance to paclitaxel, cisplatin, and carboplatin." (PMID 26198101, 2015). "Using a highly aggressive and metastatic ovarian cancer cell line (HEY) which sustains high endogenous expression of Oct4A, we show that suppression of Oct4A resulted in the loss of CSC-associated expression of Lin28, Sox-2, EpCAM and CD44." (PMID 26260289, 2015). "The results indicate that NANOG alone or in combination with SOX2 may contribute to the transformation of ovarian endometriosis to ovarian cancer." (PMID 24884521, 2014). "Gene knockdown of SOX2 suppressed the tumor-initiation of ovarian cancer cells." (PMID 23967051, 2013). "Thus, the prognostic value of SOX2 in ovarian cancer must be further investigated." (PMID 36551731, 2022). "SOX2 antibodies are not usually found in association with other tumours such as teratoma, breast or ovarian cancer, whether a neurological paraneoplastic disorder is present or not." (PMID 30445363, 2019). "In addition, SOX2 was reported to enhance migration and invasion of ovarian cancer cells." (PMID 27049920, 2016). "To test whether the expansion of SOX2-expressing cells occurred prior to HGSOC development, we analyzed the fallopian tubes of 48 women at high risk of developing ovarian cancer because they were BRCA1 or BRCA2 gene mutation carriers and therefore underwent prophylactic salpingo-oophorectomy." (PMID 27492892, 2016). "Previous work suggested SOX2 regulates tumorigenic features and EMT processes by modulation of MMP2 and MMP9 activity in human CRC and ovarian cancer cells." (PMID 40179020, 2025). "We previously showed that SOX2, relative to OCT4 or NANOG, is a better marker of drug-resistant CSCs in ovarian cancer." (PMID 39287565, 2024).
ovarian carcinoma (continued). "FOXP1 functions as an oncogene in epithelial ovarian cancer cells by promoting the CSC-like characteristics, while its overexpression led to an up-regulated expression of ABCG2, OCT4, NANOG, and SOX2 genes and protected cells against apoptotic cell death." (PMID 37189618, 2023). "In ovarian cancer, SMAD1 positively regulates SOX2 and SMAD3 negatively regulates SOX2, which acts as a regulatory node that controls the signalling of the TGF-β pathway, which in turn affects ovarian cancer metastasis." (PMID 37685308, 2023). "Another study showed that SOX2 is a transcription factor of FN1 that promotes the migration and invasion of ovarian cancer cells." (PMID 36601474, 2022). "The interaction of SOX-2 with PHF20L1 has already been demonstrated by others; SOX-2 and PHF8, another PHD finger protein, have been analyzed in ovarian cancer tumor tissues, showing that SOX-2 was overexpressed in mucinous carcinoma." (PMID 34991589, 2022). "Finally, the present study demonstrated that the AMPK signalling pathway regulates pluripotency factor expression (Sox2, Oct4 and Nanog) in ovarian cancer cells, suggesting that strategies targeting AMPK might provide a novel approach to control the cancer stem cells of EOC patients." (PMID 36114703, 2022). "First, a meta-analysis based on the TCGA database found that PD-L1 expression was closely correlated with MYC, SOX2, and SNAI1 in the endometrial and ovarian cancer data sets." (PMID 36582540, 2022). "A better understanding of how SOX2 contributes to TIC biology will lead to more effective therapeutic strategies for preventing relapse and prolonging remission for ovarian cancer patients." (PMID 33445692, 2021). "In ovarian cancer, HIF-1α activates Notch1 signaling, which increases the activity of the Sox2 promoter, creating a CSC phenotype and drives drug resistance in ovarian cancer stem cells." (PMID 34867818, 2021). "The expression level of CD133 is elevated in sphere-forming and drug-resistant populations of ovarian cancer cells, which exhibit chemoresistance and tumorigenesis in vivo and increased levels of stemness markers such as OCT4, SOX2, and NANOG." (PMID 34064635, 2021). "Additionally, while the presence of traditional CSC markers (CD117, CD133, ALDH1) was variable across cell lines, SOX2 was consistently increased in 3D conditions, and elevated in recurrent cases of ovarian cancer, suggesting it may be a more reliable functional marker of CSC and disease recurrence." (PMID 34283069, 2021). "Taken together, these data highlight the heterogeneous expression of TIC genes across ovarian cancer cell lines and suggest that HGSOC lines have consistent enrichment of SOX2, OCT4 and NANOG that correlates with specific TIC markers." (PMID 33445692, 2021). "SOX2, OCT4, and NANOG are enriched in ovarian cancer spheroids and correlate with tumor-initiating cell markers, CD117 and ALDH/CD133." (PMID 33445692, 2021). "In ovarian cancer cells, exposure to hypoxia increases expression of CD44, CD133, Oct3/4 and Sox2, which are known markers of ovarian CSCs." (PMID 34867818, 2021). "Treatment with CM37, a small molecule with inhibitory activity against ALDH1A1, suppressed spheroid proliferation of ovarian cancer cells and reduced expression of OCT4 and SOX2 in ALDH+ cells in ascites and ovarian cancer cell lines." (PMID 35582216, 2020). "To validate if PRL-3-high tumors really have high level of SOX2 in clinical samples, we collected and examined both PRL-3 and Sox2 expressions in 37 fresh ovarian cancer samples." (PMID 31887658, 2020). "Ovarian cancer stem cells (CSCs), also known as cancer-initiating cells, are characterized by cell surface expression of CD24, CD44, CD117 (KIT), SOX2, and NANOG." (PMID 32823589, 2020).
ovarian carcinoma (continued). "At the same time, the expression level of ALKBH5 was significantly increased in SKOV‐3 and Ishikawa co‐cultured cells; meanwhile, all the expression levels of NANOG, SOX‐2 and OCT‐4 increased in ovarian cancer tissues, but fell in ovarian cancer cell lines." (PMID 32329191, 2020). "We first analyzed The Cancer Genome Atlas (TCGA) databases for copy number alterations in SOX2 and ST6GAL1 and showed that these two genes are coordinately amplified in patient specimens across a wide range of cancer types, including ovarian cancer." (PMID 31610800, 2019). "Sox2, a pluripotent stem cell (PSC) protein, is frequently expressed in many poor prognosis tumors and co-expressed with Oct4 and Lin28 in ovarian cancer." (PMID 30064416, 2018). "Our meta-analysis demonstrated that PD-L1 is co-amplified along with MYC, SOX2, N-cadherin and SNAI1 in the TCGA endometrial and ovarian cancer datasets." (PMID 30283733, 2018). "These enriched and expanded CD8+ CIK cells from CIK had significant cytotoxic activity against K562 and ovarian cancer cells, which expressed HLA-I and OCT4 and Sox2." (PMID 28426690, 2017). "Taken together, these results demonstrated that that ovarian cancer cells expressed HLA-I molecules and OCT4, and OVCAR3 cells expressed Sox2." (PMID 28426690, 2017). "In the current study, we explored the roles of hypoxia, NOTCH1, and SOX2 in the sphere-forming ability, drug resistance, and CSC marker expression of CSC-like cells isolated from ovarian cancer cell lines and primary ovarian cancer cells." (PMID 27489349, 2016). "DAPT treatment, SOX2 knockdown, and combination of DAPT treatment and SOX2 knockdown decreased sphere forming activity of A2780 ovarian cancer cells." (PMID 27489349, 2016). "In conclusion, we show that CSC characteristics in not only ovarian cancer cell lines but also primary CSCs are augmented in hypoxic condition, and NOTCH1 and SOX2 are important mediators of hypoxia in ovarian CSCs." (PMID 27489349, 2016). "And c-kit, along with Oct4, Nanog, SOX2, CD133, CD44, and ALDH1, has been considered as a cancer stem cell marker in primary non-small cell lung cancer (NSCLC), ovarian cancer and hepatocellular carcinoma." (PMID 26958807, 2016). "In support of the results, hypoxic pretreatment of ovarian cancer cells, ES-2 and OVCAR-3, increased expression of OCT4 and SOX2 and stem-like properties including sphere formation, high proliferation, and high infiltration." (PMID 27489349, 2016). "AuNPs inhibit cisplatin induced EMT, decrease the side population cells and key stem cell markers such as ALDH1, CD44, CD133, Sox2, MDR1 and ABCG2 in ovarian cancer cells." (PMID 25071019, 2014). "Moreover, SOX-2 was also found to induce resistance by increasing anti-apoptotic proteins like Bcl-2 and decreasing pro-apoptotic proteins like PUMA/BBC3 in ovarian cancer cells." (PMID 38864530, 2024). "As with primary ovarian cancer OvCa3 A, the OvCa7 A cells were negative for Sox2, and positive for Oct4 and Nanog." (PMID 38791431, 2024). "In our current study, we found that THP1-and PBMC-derived macrophages did not promote expression of SOX2 in ovarian cancer cells when co-cultured for 48 hours without cytotoxic drugs." (PMID 39287565, 2024). "Another study revealed that RP11-499E18.1 may have tumor suppressor functions by lowering the nuclear translocation of p-SOX2 and dissociating the relationship between PAK2 and SOX2 in ovarian cancer." (PMID 39769207, 2024). "The results of various studies have suggested that the expressions of stem cell markers, such as NANOG, SOX2, forkhead-box protein M1 (FOXM1), and OCT4, in ovarian cancer mirror their tumorigenic potential, as well as resistance to paclitaxel, cisplatin, methotrexate, and adriamycin cells." (PMID 38201468, 2023).
ovarian carcinoma (continued). "Wnt signaling also plays a key role in tumor stem cells: activation of Wnt/β-catenin signaling pathway can promote the tumor stem cell characteristics of ovarian cancer cells and esophageal cancer cells, possibly through upregulation of tumor stem cell markers Nanog, OCT-4, and SOX2." (PMID 35979255, 2022). "Further experiments showed that the stemness markers including KLF4, SOX2, and CD133 were increased by IL-8 stimulation, suggesting that IL-8 secreted from CAFs may promote ovarian cancer cell stemness." (PMID 34277625, 2021). "SOX2, but not OCT4 or NANOG, has been implicated in early tumor initiation and plays a more substantial role in tumor relapse in ovarian cancer patients." (PMID 34064635, 2021). "Our previous study showed that hypoxia-induced NOTCH and HIF-1α elevated SOX2 expression to promote sphere formation and drug resistance by increasing ALDH1, ATP-Binding Cassette Subfamily B Member 1 (ABCB1), and ABCG2 expression in ovarian cancer cells." (PMID 34064635, 2021). "Green fluorescent protein (GFP)-labeled ovarian CSCs utilize the NANOG promoter system to overexpress OCT4, SOX2, and NANOG compared with the GFP-negative ovarian cancer cells, and the GFP-positive cells also exhibit greater cisplatin resistance and tumor initiation properties." (PMID 34064635, 2021). "Ovarian cancer cell lines that failed to express SOX2 were sensitive to carboplatin, cisplatin, and paclitaxel developed resistance following the ectopic expression of SOX215." (PMID 32144236, 2020). "In addition, The Cancer Genome Atlas datasets of ovarian cancer clinical samples analysis validated a good correlation between PRL-3 and SOX2 expressions at mRNA levels (n = 295)." (PMID 31887658, 2020). "Clinical relevance among PRL-3, SOX2, and HDAC4 is validated in ovary cancer samples." (PMID 31887658, 2020). "Several putative ovarian cancer stem cell markers, such as CD24, CD44, CD133, SOX2, SSEA have been proposed, but the definition of their phenotypical features remains highly variable in the various studies, probably due to the consistent phenotypic and functional plasticity of these cells." (PMID 29389895, 2018). "Expression of stem cell markers (OCT4, SOX2, NANOG, NESTIN, ABCG2, CD133 and CD117) in ovarian cancer (sphere cells) represent their tumorigenic potential, and resistance to cisplatin, paclitaxel, adriamycin and methotrexate, which highlights the significance of “stemness” of cancer cells." (PMID 30121075, 2018). "SOX2 expression in primary ovarian cancer samples was heterogeneous and positive cases displayed not more than 10% positive cells." (PMID 29389895, 2018). "To this end, we determined the gene expression of Sox2 and OCT4 in ovarian cancer cells by qPCR." (PMID 28426690, 2017). "Moreover, the abundance of KDM3A was positively correlated with Sox2 levels, indicating the functional significance of KDM3A in human ovarian cancer." (PMID 27694900, 2017). "The aim of this study was to focus on in situ morphological changes in the ovarian surface epithelium of tumor tissue in women with epithelial ovarian cancer after we applied the antibodies for markers of EMT vimentin and pluripotency-related markers NANOG, SOX2 and SSEA-4." (PMID 28231820, 2017). "Our results indicated that CD8+ T cells in healthy adults might have immunological memory capacity to OCT4 and Sox2, suggesting that CD8+ CIK cells may kill ovarian cancer cells via binding OCT4 and Sox2 antigens." (PMID 28426690, 2017). "In ovarian cancer, hypoxic microenvironment is known to increase CSC characteristics including sphere formation, the higher proliferation, the higher infiltration, and expression of OCT4 and SOX2." (PMID 27489349, 2016). "In contrast, in breast and ovarian carcinoma SOX2 expression occurs in the absence of SOX2 gene amplifications and appears enriched in putative CSCs." (PMID 26498353, 2015).